NF1 (neurofibromin 1)
Diseases named in the same sentence as NF1 in open-access papers (continued):
Sharing a sentence is not in itself a finding about the gene and the disease.
Williams syndrome (9 papers, 2011 to 2025). "MAS can be associated with genetic disorders including neurofibromatosis-1 (NF-1), Williams syndrome, and Alagille syndrome." (PMID 36660171, 2023). "We found that both the CD model of Williams Syndrome and the Nf1+/R681X model of a patient-derived NF1 mutation shared multiple spatial, temporal, and postural developmental gait abnormalities." (PMID 33743598, 2021). "The treatment of RAS with PTRA may be difficult because of arterial wall thinning, friability, and the firm elastic recoil of the intramural lesion in some conditions such as NF-1, William syndrome, or mid-aortic syndrome." (PMID 26564026, 2015).
attention deficit-hyperactivity disorder (8 papers, 2018 to 2025). A disorder characterized by a marked pattern of inattention and/or hyperactivity-impulsivity that is inconsistent with developmental level and clearly interferes with functioning in at least two settings (e.g. at home and at school). "Additionally, there are reports of considerable diagnostic overlap between NF1 and both attention-deficit/hyperactivity disorder (ADHD) and autism spectrum disorder." (PMID 36037004, 2022). "Approximately 30–50% of children with NF1 meet criteria for attention-deficit/hyperactivity disorder (ADHD)." (PMID 38475852, 2024). "Furthermore, approximately one third of patients with NF1 meet DSM-V criteria for attention deficit hyperactivity disorder (ADHD)." (PMID 31545171, 2019).
carcinoids (8 papers, 2005 to 2025). "However, this association is a controversial topic because of the well-established association between carcinoids and NF1 and the difficulty in distinguishing between adenocarcinomas and carcinoids histopathologically." (PMID 30187267, 2018). "Increasing molecular evidence supports the composite lesions hypothesis: shared alterations, such as KRAS, NF1, and BRAF V600E mutations, have been reported in both adenocarcinoma and carcinoid components, suggesting a monoclonal origin in select cases." (PMID 41209982, 2025). "Duodenal and ampullary carcinoids have been found in patients with NF1." (PMID 25525544, 2014).
ganglioneuroma (8 papers, 2011 to 2024). A benign neuroblastic tumor of the sympathetic nervous system that occurs in childhood. "In two cases other malignancies such as ganglioneuroma (NF_37) and optic glioma (NF_65) were associated to NF1." (PMID 35885913, 2022). "Ganglioneuroma is a low-grade tumor arising from neural crest cells, which can be sporadic or associated with cancer predisposition syndromes including neurofibromatosis type 1 (NF-1), multiple endocrine neoplasia type 2B, Cowden syndrome, and Costello syndrome." (PMID 39070150, 2024). "This is the first reported case of NF-1-related ganglioneuroma showing a clinical and radiological response to the MEK inhibitor trametinib." (PMID 39070150, 2024). "Here, we report a rare case of ganglioneuroma of the appendix pointed out during follow-up of NF1." (PMID 34581917, 2021).
lymphoma (8 papers, 2012 to 2023). A malignant (clonal) proliferation of B- lymphocytes or T- lymphocytes which involves the lymph nodes, bone marrow and/or extranodal sites. "From these findings, the differential diagnoses of this mass were lymphoma, teratoma, lung cancer or metastasis and malignancy associated with NF1, such as MPNSTs and chromaffin cells tumor." (PMID 22236362, 2012). "Lymphoma potentially occurs in NF1 patients through a series of proto-oncogene activation and mismatch repair gene mutations although the precise pathogenetic mechanism needs to be further explored." (PMID 22236362, 2012). "These included Kras (HGG, carcinoma), Nf1 (HGG), Pten (carcinoma), Myc (HGG, carcinoma) and Notch (lymphoma)." (PMID 33277484, 2020).
myeloid malignancies (8 papers, 2014 to 2023). "With the exception of an NF1-RHOT1 fusion that would result in NF1 loss-of-function, the remaining 3 fusions identified (NUP98-KDM5A, DEK-NUP214, ETV6-MECOM) are known to be associated with myeloid malignancies." (PMID 29146900, 2017). "Importantly, our observations with HQ are highly consistent with observations in human patients and in mice showing that heterozygous Nf1 inactivation cooperates strongly with genotoxins (particularly radiation) to induce myeloid malignancies and other secondary cancers." (PMID 24386979, 2014). "Although the NF1 L532R and CEBPA G268fs were not reported in Catalogue of Somatic Variants in Cancer (COSMIC), NF1 and CEBPA are quite observed in somatic variant profiles in myeloid neoplasm." (PMID 36814285, 2023).
myxofibrosarcoma (8 papers, 2011 to 2025). A malignant fibroblastic neoplasm arising from the soft tissue. "Point mutations and genomic deletions of the NF1 gene were found in 10.5% of the myxofibrosarcomas and 8% of the pleomorphic liposarcomas in 207 samples of STSs." (PMID 35559021, 2022). "More recently, human myxofibrosarcoma and pleomorphic liposarcomas were shown to frequently harbor NF1 mutations." (PMID 21533183, 2011). "We conducted fluorescence in situ hybridization (FISH) for NF1 and p16 deletions comparing 55 MPNSTs and 35 non-MPNSTs, consisting of 9 synovial sarcomas (SSs), 8 leiomyosarcomas (LMSs), 10 myxofibrosarcomas (MFSs), and 8 undifferentiated pleomorphic sarcomas (UPSs)." (PMID 34461930, 2021).
neurofibrosarcoma (8 papers, 2010 to 2022). A malignant tumor that arises from small cutaneous nerves, is locally aggressive, and has a potential for metastasis. "MPNST, a devastating neurofibrosarcoma associated with NF1, is a difficult disease to treat with current therapeutic options; however, it is particularly suitable for PDT." (PMID 28558025, 2017). "NF1 is associated with several tumors, among which are neurofibrosarcomas." (PMID 36110436, 2022). "PAK1 is required for the malignant growth of RAS transformants in NF1 neurofibrosarcoma cell lines." (PMID 32858845, 2020).
Vestibular schwannoma (8 papers, 2009 to 2026). A vestibular schwannoma (also known as acoustic neuroma, acoustic neurinoma, or acoustic neurilemoma) is a benign, usually slow-growing tumor that develops from the VIIIth cranial nerve supplying the inner ear. "The case also highlights that sensorineural hearing loss, commonly associated with both NF1 (particularly when vestibular schwannomas are present, although more common in NF2) and MS (due to demyelination of the auditory pathway), can be a shared early symptom." (PMID 40951077, 2025). "To date, mouse (and some zebrafish) models of MPNSTs, PNs, and OPGs have been developed for NF1 while a vestibular schwannoma model has been developed for NF2." (PMID 34885143, 2021). "Finally, MTVSs had a higher rate of NF syndrome (commonly NF2) compared with spinal MPNSTs (commonly NF1) (18.5% vs. 14.0%), and NF2 patients with a malignant transformation of a vestibular schwannoma may have a poorer prognosis compared to NF1 patients with spinal MPNST." (PMID 33937063, 2021).
acute lymphoblastic leukemia (7 papers, 2014 to 2025). Leukemia with an acute onset, characterized by the presence of lymphoblasts in the bone marrow and the peripheral blood. "Mutations in RAS pathway proteins (e.g., KRAS, NRAS, FLT3, PTPN11, and NF1) are highly prevalent in acute lymphoblastic leukemia (ALL), with such mutations occurring in 40%–50% of pediatric B cell ALL cases." (PMID 35243242, 2022). "The frequency of NF1 mutations in sporadic acute lymphoid leukemia (ALL) was recently reported as 3-8%." (PMID 25026295, 2014). "Children with NF-1 have a higher risk of developing juvenile myelomonocytic leukemia and acute myeloid leukemia, but rarely develop acute lymphoblastic leukemia (ALL)." (PMID 35515133, 2022).
bladder cancer (7 papers, 2018 to 2024). "Based on previous reports, mutations of ATM, NF1, and NOTCH1 in bladder cancer are found in approximately 15%, 10%, and 50% of cases, respectively." (PMID 37892022, 2023). "The most frequently mutated genes in bladder cancer samples in the present study were ATM, NF1, and NOTCH1." (PMID 37892022, 2023). "For instance, the deletion or inactivation of NF1 can disrupt normal cell cycle regulation, which might contribute to the development of bladder cancer in some autosomal mCAs carriers." (PMID 39349436, 2024). "Despite these reports, the only clinical trial that utilizes MEK inhibition in bladder cancer is the ongoing MATCH screening trial in advanced solid tumors (NCT02465060), using mutation status of BRAF, GNA11, and NF1 to identify potential responders to the MEK inhibitor, Trametinib." (PMID 33216841, 2020).
fibrosarcoma (7 papers, 2017 to 2025). A malignant mesenchymal fibroblastic neoplasm affecting the soft tissue and bone. "NF1 is a GTPase-activating protein that negatively regulates Ras, and thus, NF1 loss leads to induction of Ras/rapidly accelerated fibrosarcoma (RAF)/MEK signaling, driving tumorigenesis and comprising a targetable molecular cascade." (PMID 40985888, 2025). "MPNST with NF1 mutation leads to the promotion of the Rapidly Accelerated Fibrosarcoma/Mitogen-Activated Protein Kinase/Extracellular Signal (RAS/RAF/MEK/ERK) pathway." (PMID 39768355, 2024). "In addition to mutations in Ras, the MAPK pathway can also become activated due to mutations in the Ras-binding kinase rapidly accelerated fibrosarcoma (Raf) or to inactivating mutations in negative regulators of MAPK such as neurofibromin 1 (NF1)." (PMID 28513539, 2017). "Neurofibromin 1 (NF1) gene is an important negative regulator of the rat sarcoma virus (Ras)/rapidly accelerated fibrosarcoma (Raf) kinase activation pathway, which is an established promoter of cell proliferation." (PMID 35505937, 2022).
ganglioglioma (7 papers, 2018 to 2025). A well differentiated, slow growing neuroepithelial neoplasm composed of neoplastic, mature ganglion cells and neoplastic glial cells. "Control cases of gangliogliomas with BRAF V600E (control 1, 2) and NF1 association (control 3) showed strong Cyclin D1 expression indicating MAPK pathway activation, while there was no nuclear NFκB staining." (PMID 40234994, 2025).
Hydrocephalus (7 papers, 2012 to 2022). Hydrocephalus is an active distension of the ventricular system of the brain resulting from inadequate passage of CSF from its point of production within the cerebral ventricles to its point of absorption into the systemic circulation. "Only around 1% of all NF-1 patients additionally develop brainstem gliomas with a risk of hydrocephalus due to secondary obstructive hydrocephalus." (PMID 34828788, 2021). "Other risk factors include being female, the NF-1 mutation, an extension of the surgical resection, hydrocephalus, protocols including neurotoxic CT (especially high dose methotrexate), tumor location, and the irradiated brain volume." (PMID 31860688, 2019). "The relationship between CSF-related disorders (especially hydrocephalus) and NF-1 has already been reported." (PMID 31655505, 2019). "The authors have already described three children: patient 10 patient 11 and patient 16, respectively in paper focused on association of NF1 with MMS, hydrocephalus and a benign phenotype associated to Arg1809 substitution." (PMID 29566708, 2018). "Previous studies have found ventriculomegaly, generalized enlargement of the pericerebral spaces, and dilated ventricles in fetuses, as well as Chiari I with hydrocephalus, septum cavum pellucidum, and agenesis of the corpus callosum in patients with NF1 microdeletions and variants." (PMID 35562572, 2022). "Age <1 year at diagnosis, DS, hydrocephalus, absence of NF1, MDC3/4, and H+ were independent predictors at OPHG diagnosis of future development of APD in univariate Cox regression analysis." (PMID 35159015, 2022).
Lynch syndrome (7 papers, 2018 to 2024). An autosomal dominant hereditary neoplastic syndrome characterized by the development of colorectal carcinoma and a high risk of developing endometrial carcinoma, gastric carcinoma, ovarian carcinoma, renal pelvis carcinoma, and small intestinal carcinoma. "Similarly to studies on Western populations, mutations in genes other than those associated with the Lynch syndrome, including MUTYH, BRCA2, ATM, BRIP1, CDKN2A, and NF1, were identified." (PMID 39061183, 2024).
myelodysplastic syndrome (7 papers, 2014 to 2022). A clonal hematopoietic disorder characterized by dysplasia and ineffective hematopoiesis in one or more of the hematopoietic cell lines. "Along these lines, recent work evaluating the role of gene mutations on the prognosis of myelodysplastic syndromes demonstrated that patients with mutations in KRAS or NF1 show worse OS than patients with NRAS or CBL mutations." (PMID 29259247, 2017). "Heterozygous Nf1 mutant mice are also susceptible to myelodysplastic syndrome (MDS) and other genotoxin-induced cancers, and appear to be particularly sensitive to the mutagenic effects of radiation." (PMID 24386979, 2014). "Limited data suggests the frequency of NF1 alterations in myelodysplastic syndrome (MDS) varies from 0% to 9%." (PMID 25026295, 2014). "In addition, EZH2 loss significantly promoted the development of myelodysplastic syndrome induced by transcription factor Runx1 mutation, and loss of SUZ12 synergizes with neurofibromin 1 (NF1) mutations to amplify Ras signaling to drive cancer." (PMID 36076977, 2022). "Myelodysplastic syndromes are shaped by gene aberrations involved in NF1 and SF3B1." (PMID 31466283, 2019).
Obesity (7 papers, 2021 to 2025). Accumulation of substantial excess body fat. "The comprehensive vascular screening was performed in five women with NF1 (11.4%) because of additional risk factors for vascular complications, such as obesity or a family history of cardiovascular complications (data not shown)." (PMID 37337089, 2023).
ovarian tumors (7 papers, 2011 to 2026). "Rather than acting as a direct prognostic determinant, NF1 mutation appears to increase vulnerability to replication stress and DNA damage, providing functional insight into its role in ovarian tumor biology." (PMID 42158468, 2026).
Pseudoarthrosis (7 papers, 2011 to 2025). A pathologic entity characterized by a developmental defect in a long bone leading to bending and pathologic fracture, with inability to form a normal bony callus with subsequent fibrous nonunion, leading to the pseudarthrosis (or "false joint"). "NF1-related bone deformities were present in nine patients (10%), all with sphenoid wing dysplasia, combined with pseudoarthrosis in two." (PMID 39796750, 2025). "Four different cases of non-unions were discussed: non-union induced by periosteal and endosteal injury, non-union due to a large interfragmentary gap, non-union due to a genetic disorder (i.e. NF1 related congenital pseudoarthrosis of the tibia (CPT)) and non-union due to mechanical overload." (PMID 26709368, 2015).
Renal artery stenosis (7 papers, 2014 to 2025). The presence of stenosis of the renal artery. "Although renal artery stenosis and aneurysm formation have been reported in patients with NF-1, to our knowledge SRAD has not been previously reported." (PMID 27867667, 2016).
serous ovarian cancer (7 papers, 2014 to 2026). "Additionally, NF1 is a common variant gene in high‐grade serous ovarian cancer, and its mutation is correlated to platinum‐based chemotherapy resistance in this cancer." (PMID 33934540, 2021). "In addition, this panel is targeting “hotspot” region of genes that are frequently mutated in human cancer thus other infrequently altered genes but of significance to serous ovarian cancers might have been excluded such as ARID1A, BRCA1, BRCA2, CSMD3, NF1, CDK12, FAT3 and GABRA6." (PMID 25404506, 2014).
somatostatinoma (7 papers, 2005 to 2024). A rare, usually malignant neuroendocrine tumor arizing from delta cells. "Many are classified as somatostatinomas, and NF1 has rarely been associated with insulinomas and gastrinomas." (PMID 16042772, 2005). "Our finding of gastrinoma contrasts with the most prevalent type of peri-ampullary NETs observed in patients with NF-1, which is somatostatinoma (40%)." (PMID 39403336, 2024). "PanNENs, not being part of the classic features of NF-1, are present in fewer than 10% and are almost exclusively duodenal somatostatinomas located in the peri-ampullar region, which does not secrete hormones but frequently causes jaunice, biliary dilatation and pancreatitis." (PMID 34885063, 2021).
anemia (6 papers, 2017 to 2024). A reduction in the number of red blood cells, the amount of hemoglobin, and/or the volume of packed red blood cells. "A 68-year-old man with NF1 presented with melena and was diagnosed with anemia due to bleeding from multiple small intestinal GISTs." (PMID 39542941, 2024). "In previous study, Santasree Banerjee and his co-workers (2017) presented a clinical molecular study of four Chinese probands with NF1 from four unrelated families, showing extreme phenotypic variation with rare phenotype, tibial pseudarthrosis, and anemia." (PMID 37095468, 2023).
Angelman syndrome (6 papers, 2010 to 2023). A neurogenetic disorder characterized by severe intellectual deficit and distinct facial dysmorphic features. "For example we identified an individual with undiagnosed Angelman’s syndrome type 2 and an individual with an NF1 deletion." (PMID 27650969, 2016). "Challenges in mapping adult Irish clinical experts for lifelong, childhood-onset neurodevelopmental conditions, such as NF1, 22q11 deletion syndrome and Angelman syndrome, revealed significant gaps in adult service provision due to a lack of clear transition pathways." (PMID 35410222, 2022).
angiosarcoma (6 papers, 2014 to 2022). A malignant tumor arising from the endothelial cells of the blood vessels. "We present a case of 12.5-year-old girl with NF1 who first presented with MPNST of the right inguinal region and 1.5 years later with unrelated angiosarcoma of the scalp." (PMID 29138703, 2017). "Four (including one with angiosarcoma component) of them with NF1 had no metastasis at diagnosis, and only two survived longer than 12 months." (PMID 24971186, 2014).